PRMT5 (protein arginine methyltransferase 5)
Diseases named in the same sentence as PRMT5 in open-access papers (continued):
Sharing a sentence is not in itself a finding about the gene and the disease.
cancer (continued). "The expression of FBW7, a tumor suppressor, is often reduced in human cancer cells; however, knockdown of PRMT5 in PDAC cells elevated its expression, indicating that PRMT5 regulates FBW7 expression." (PMID 38612768, 2024). "Further investigations into the specific interactions and downstream effects of PRMT5 in HCC development are warranted to fully comprehend its role and therapeutic implications in combating this aggressive form of cancer." (PMID 38666828, 2024). "PRMT5 regulates key BC pathways, including cell cycle, EMT, DNA damage repair, cancer stem cell maintenance, and gene expression through histone modification and chromatin remodeling." (PMID 39201539, 2024). "The interaction between ENO1 and other proteins, such as protein arginine methyltransferase 5 (PRMT5), further exhibits its impact on cancer." (PMID 38611852, 2024). "PRMT5 has been shown to decrease the level of type I interferon (IFN) and chemokine production and repress antigen presentation, suppressing cancer cell recognition by T cells." (PMID 39201539, 2024). "Domain-focused CRISPR screening in cancer lines including HSC5 revealed that control cells outnumbered PRMT5KO cells, indicating that PRMT5 was essential for viability." (PMID 39594744, 2024). "Next, we analysed the functional effects of the interaction between PRMT5 and STAT3 in cancer cells." (PMID 38760429, 2024). "MTA competed with SAM for binding to PRMT5 as an endogenous inhibitor, and the reduction of SAM was deduced to sensitize the effect of MTA‐cooperative inhibitors in MTAP‐deleted cancer cells." (PMID 39309689, 2024). "Our findings suggest that PRMT5-mediated FXR1 methylation is required for RNA/G4-RNA binding, which promotes gene expression in cancer cells." (PMID 38709899, 2024). "Next, we investigated the capacity of PRMT5/1i to inhibit FXR1 mRNA transcript and protein levels in cancer cells." (PMID 38709899, 2024). "Therapeutic strategies that are proven effective in MTAP‐deleted cancers such as PRMT5 inhibitors and MTA‐cooperative PRMT5 inhibitors should be investigated in the context of low MTA AML." (PMID 39259513, 2024). "Treatment with the PRMT5-specific inhibitors CMP5 and HLCL61 was more sensitive in NDRG2low cancer cells than in NDRG2-expressing cells via the inhibition of HSP90 arginine methylation, along with the degradation of client proteins." (PMID 38474089, 2024). "The reduction of SAM, along with the accumulation of MTA, contributes to reducing PRMT5 activity and leads to antiproliferative effects in MTAP‐deleted cancer cells and tumors." (PMID 39309689, 2024). "To confirm the relationship of cancer vulnerability between low NDRG2 expression and PRMT5/MEP50 activity, we used three recently developed potent and specific PRMT5 inhibitors (EPZ015866, CMP5, and HLCL61)." (PMID 38474089, 2024). "PRMT5 expression is also induced by STAT3, suggesting the presence of a positive feedback loop in cancer cells." (PMID 38760429, 2024). "To interrogate the oncogenic functions and gene signatures essential for cancer cell growth and proliferation, we performed an RNA-seq by silencing FXR1 and PRMT5 separately using shRNAs and analyzed the high-throughput sequencing data." (PMID 38709899, 2024). "Our data adds to the growing body of evidence indicating cell cycle pathways are profoundly affected by SNRPD3 or PRMT5 inhibition, suggesting that combination therapy between PRMT5 and cell cycle inhibitors may be a promising avenue for further exploration in cancer therapeutics." (PMID 38049564, 2024). "In GSE36376, the expressions of PRMT1, PRMT2, PRMT3, PRMT4, PRMT5, and PRMT7 were upregulated in cancer tissues." (PMID 37627211, 2023). "Both PRMT5 and E2F1 regulated the expression of lncRNA genes and therefore impacted on the repertoire of peptides presented to the immune system by cancer cells." (PMID 36841868, 2023). "Thus, targeting PRMT5 may offer a novel and effective approach to cancer therapy." (PMID 37461162, 2023).
cancer (continued). "Other molecules, such as FOXA1, SETD2, Hes5, C/EBP-δ, PRMT5, METTL3, Piwil1, PLK1, ERK1/2, and a series of miRNA, indirectly modulate the sensitivity of cancer cells to drugs by regulating FBXW7." (PMID 36998461, 2023). "Subsequently compounds have recently been produced that interact with PRMT5 when bound to MTA, and which selectively target MTAP-negative cancer cells to varying degrees or elicit a synergistic effect in a MTAP-negative background." (PMID 37795443, 2023). "Potent and selective PRMT5 inhibitors significantly downregulate expression of multiple DDR and DNA replication genes in cancer cells." (PMID 37861290, 2023). "Our data support a conserved role for PRMT5 in regulating expression of DDR-realted and DNA replication–related genes in cancer cells, which can be blunted by PRMT5 inhibitors." (PMID 37861290, 2023). "In cancer tissues of GSE25097, the expressions of PRMT2, PRMT3, PRMT4, PRMT5, and PRMT7 were upregulated in cancer tissues, whereas the expressions of PRMT6 and PRMT9 were downregulated." (PMID 37627211, 2023). "Further, PRMT5/E2F1 expression and cortactin/CTTN expression showed positive correlations across different types of cancer in the Cancer Genome Atlas datasets (TCGA), suggesting that E2F1 and PRMT5 regulate the process of cell migration and invasion." (PMID 37795443, 2023). "It is through this interplay that both PRMT5 and E2F1 are able to regulate antigen presentation by cancer cells." (PMID 36841868, 2023). "Mechanistically, PRMT5 induces DDR genes (HR, NHEJ, G2 arrest) upon IR-induced DNA DSBs and therefore assists the cancer cells to recover and resist the effect of IR." (PMID 36959798, 2023). "However, there is not enough evidence to elucidate the major functions of PRMT5 in CRC cell metabolism, especially the relevant roles of PRMT5 in glycolysis pathway and whether PRMT5 sustains cancer tumorigenicity through regulating glycolytic enzymes have seldom been discussed." (PMID 36474242, 2022). "Although PRMT5 has been reported to methylate H3R8, H3R2, and H4R3 to facilitate transcriptional activation or regression in cancer, there are few studies related to the exact site methylated by PRMT5 in the process of CRC metastasis." (PMID 35429301, 2022). "In sum, these data suggest PRMT5‐mediated sDMA modification negatively regulates the stability of vimentin, and the stabilized vimentin compels the invasion of MTAP‐deleted cancer." (PMID 35766227, 2022). "FOXD2-AS1 acts as a scaffold for STAT3 and PRMT5, promoting STAT3 transcriptional activity, essential to maintain cancer stemness and promote chemotherapeutic resistance." (PMID 35978835, 2022). "Previous studies on arginine methyltransferases in cancers have mostly focused on PRMT1, CARM1, and PRMT5." (PMID 36199122, 2022). "Moreover, the MTAP‐ and PRMT5‐mediated sDMA modification negatively regulates the stability of vimentin protein via proteasomal degradation, as evidenced by the observations from two independent cohorts, Taiwan Cancer Moonshot proteogenomic data and tissue microarray IHC staining data." (PMID 35766227, 2022). "Previous studies have demonstrated that both PRMT5 and MSI2 maintain c-MYC expression in cancer cells through independent mechanisms, but we found MSI2 and PRMT5 cooperate by retaining c-MYC translation." (PMID 36167829, 2022). "It has been found that expression of certain PRMT genes is altered in some cancer types such as PRMT1 and CARM1 overexpressed in breast and prostate cancers or PRMT5 and PRMT6 overexpressed in lung and blood cancers." (PMID 36358861, 2022). "There have been various promising examples of the development of protein methyltransferase inhibitors for cancer therapy, such as EZH2 and PRMT5 inhibitors, and some have undergone clinical trials." (PMID 36421786, 2022).
cancer (continued). "Another forkhead box (FOX) reported as important for laryngeal SCC DR is FOXD2-AS1, which acts as a scaffold for STAT3 and PRMT5, promoting STAT3 transcriptional activity, maintaining cancer stemness, and promoting chemotherapeutic resistance." (PMID 35978835, 2022). "It was proposed that cancer cells with high MYC activity, which leads to an increased total RNA burden, rely on PRMT5 to orchestrate splicing fidelity." (PMID 35439169, 2022). "In sum, PRMT5 is a therapeutic target in PDAC, and high mRNA expression of the arginine methyltransferase marks cancers with high MYC expression and network activity." (PMID 35439169, 2022). "Inhibiting PRMT5 increased the chemotherapeutic effect of cisplatin and gemcitabine, and co-treatment of PRMT5 and EGFR inhibitor significantly inhibited cancer cell growth." (PMID 36199122, 2022). "Abnormal expression of PRMT5, MEP50, or WDR5 are found in many cancers and often correlated with malignant progression of tumor indicates that PRMT5/MEP50/WDR5 complexes plays an important role in cancer progression." (PMID 35987690, 2022). "Over the past decades, multiple epigenetic regulators have been identified as modulators of the EMT program in various cancer cell lines in 2D, e.g., HDAC, DNMT, LSD1, KDM6B, PRMT5, EZH2, and G9a67–76." (PMID 34253738, 2021). "This study is especially important in light of the complex regulation of GLI1 and GLI2 by PRMT1, PRMT5, and PRMT7 that controls cell senescence, self-renewal with potentially far-reaching implications in pluripotency and cancer-initiating cell biology." (PMID 34440512, 2021). "Arginine residues 50 of ENO1 is methylated by protein arginine methyltransferase 5 (PRMT5) that plays an important role for increasing cell invasion and migration in cancer." (PMID 34671213, 2021). "In this study, PRMT5 protected NSCLC cells from caspase activation and apoptosis induced by anti-cancer drugs, and knocking down its expression led to CFLAR downregulation and activating chemotherapeutic-induced apoptosis." (PMID 34200178, 2021). "Several PRMT5 inhibitors, such as GSK3326595, are on clinical trial for the treatment of a variety of cancers including breast cancer." (PMID 34103528, 2021). "Among the nine members of the PRMT family, PRMT5, PRMT1, and CARM1 are most highly expressed in cancer." (PMID 34513846, 2021). "Due to the intracellular accumulation of methylthioadenosine (MTA), an endogenous PRMT5 antagonist, MTAP deletion renders cancer cells sensitive to PRMT5." (PMID 34006904, 2021). "Human methyltransferases, such EZH2, PRMT5, and DOT1L, are being actively pursued as drug targets for various cancers." (PMID 34285249, 2021). "Taken together, PRMT4, PRMT5, PRMT7 and potentially hnRNPA1 arginine methylation were required for the growth of multiple types of cancer cells." (PMID 33782401, 2021). "PRMT5 as a target has its merit, but overall, further research is needed to maximize its utilisation in PDAC cancer care." (PMID 34680285, 2021). "Since the loss of MTAP leads to the accumulation of MTA, an endogenous PRMT5 inhibitor, GSK3368715 can be effective in MTAP-null cancer cells by mediating the blockage of the compensatory relationship between ADMA and SDMA107." (PMID 34006904, 2021). "Stress induced by DNA damage increases PRMT5 protein levels and subsequently facilitates the methylation and accumulation of KLF4, modulating the cell cycle and survival of cancer cells." (PMID 34006904, 2021). "MTAP-deleted cancer cells accumulate methylthioadenosine (MTA), which inhibits the methyltransferase activity of protein arginine methyltransferase 5 (PRMT5)." (PMID 34526971, 2021). "The downstream inhibition of PRMT5 is similar to the effects of a MAT2A inhibitor in an MTAP−/− cell line, in that both inhibit cancer cell growth via restriction of PRMT5 activity." (PMID 33893330, 2021).
cancer (continued). "Based on the roles of PRMT5, Snail, and MTA1 in EMT and cancer progression, we then further identified the functional coordination of the Snail/PRMT5/NuRD(MTA1) complex on target promoters using transwell assays." (PMID 33953349, 2021). "In the presence of increased cellular glucose, PRMT5 has been shown to stimulate the release of cyclin dependent kinase 4 (CDK4) from its inhibitor, promoting G1-S transition in cancer cells." (PMID 33440687, 2021). "The significant investigation into the design of PRMT5 and MAT2A inhibitors in recent years makes the possibility of co-inhibition of MTAP a new possibility for MTAP+/+cancers as well as its use as a monotherapy." (PMID 33893330, 2021). "Further investigation is necessary to define the effects of pharmacologic inhibition of PRMT5 and its safety margin in MYC-dependent cancers." (PMID 32481522, 2020). "Protein arginine methyltransferase 5 (PRMT5) is a druggable enzyme that has been shown to be aberrantly expressed in various cancers, and it acts as a putative oncogene in maintaining cancer cell survival, yet its role in OS remains elusive." (PMID 32023548, 2020). "Given the importance of IRES-dependent protein translation under stress conditions, PRMT5 control of IRES-dependent translation likely sustains oncogenic phenotypes under oxygen and nutrient deprivation, which are commonly seen in cancer." (PMID 32743345, 2020). "A potential therapeutic angle of this phenomenon was exposed in a synthetic lethal approach that identified PRMT5 as a vulnerability of cancers with MTAP deletion, because the elevated MTA levels in these cancers already limit necessary PRMT5 activity." (PMID 32276408, 2020). "These provide the foundation for clinical evaluation of PRMT5 (four clinical trials) and PRMT1 (one clinical trial) in cancer therapy." (PMID 32743345, 2020). "PRMT5 was found to be upregulated in BUC tissue in the Oncomine and The Cancer Genome Atlas databases." (PMID 32392182, 2020). "The impact of phosphorylated PRMT5 and YBX1 on NF-κB signaling in cancer, amongst other regulators, underscores the relevance of phosphorylation in aiding tumor progression." (PMID 33375283, 2020). "Normal cells or cancers with intact MTAP, and thus high flux through the methionine salvage pathway, are less sensitive to PRMT5 inhibition." (PMID 32276408, 2020). "Recent reports revealed PRMT1, PRMT5, and PRMT7 regulate GLI1 and GLI2 activity in normal and cancer cells." (PMID 32859041, 2020). "FOXD2-AS1 acted as a scaffold for STAT3 and PRMT5, promoting STAT3 transcriptional activity, which is essential to maintain cancer stemness and promote chemotherapeutic resistance." (PMID 31959918, 2020). "PRMT5, the major type II PRMT is essential for normal development and was shown to be overexpressed in a wide variety of cancers, such as prostate, breast, lung and colon cancer." (PMID 31139329, 2019). "Protein expression of GLI1 was reduced by MEP50 or PRMT5 knockdowns, suggesting that MEP50/PRMT5-mediated activation of HH signalling operates in HH-expressing cancer cells." (PMID 30675521, 2019). "Taken together, we conclude that PRMT5 and PRMT1 truly affect apoptosis induced by anti-cancer drugs doxorubicin and pemetrexed in NSCLC cells." (PMID 30736843, 2019). "Further, in contrast to data found in cancer cells, mTOR activity was dispensable for MYC protein induction in naive and memory murine T cells, regulating PRMT5 expression via downregulation of Prmt5-targeting miRNAs or alternate mechanisms." (PMID 30941147, 2019). "Among the targets in our chemical probe collection, several have agents currently in clinical trials for cancer (EZH2, EED, DOT1L, PRMT1, and PRMT5) and additional PMT inhibitors are in preclinical studies." (PMID 30604761, 2019). "The emerging evidence reveals that protein arginine methyltransferase 5 (PRMT5) is involved in regulation of tumour cell proliferation and cancer development." (PMID 30461193, 2019).
cancer (continued). "Disruption of the PRMT5/CDK4 interaction revealed PRMT5 knockdown HepG2 cells to be more sensitive to the CDK4 inhibitor fascaplysin, marking the combination of PRMT5 and CDK4 inhibition as a potential cancer therapy." (PMID 29568320, 2018). "PRMT5, the major arginine methyltransferase catalyzing SDMA modifications is commonly activated in cancers." (PMID 29718323, 2018). "In this study, we found that PRMT5 was overexpressed in HCC and that PRMT5 promoted in vitro and in vivo cancer cell growth." (PMID 29441724, 2018). "Collectively, these studies indicate that PRMT5 overexpression may lead to its interaction with both growth promoting and tumor suppressor proteins, thereby influencing their biological activities in such a way to favor cancer cell growth, survival and invasiveness." (PMID 30613353, 2018). "While early studies showed that episomal expression of PRMT5 induces transformation of immortalized NIH3T3 fibroblasts in vitro, more recent work showed that PRMT5 inhibition in cancer cells results in growth arrest and death both in vitro and in vivo." (PMID 30613353, 2018). "Since various studies have indicated the significance of epigenetic changes in cancers and autism spectrum diseases, it would be interesting to determine how E6AP-mediated PRMT5 ubiquitination is involved in the pathobiology of those diseases." (PMID 29263404, 2017). "Our previous studies have identified several exogenous lectins such as DlFBL, Anguilla japonica lectin 1, as well as Strongylocentrotus purpuratus rhamnose binding lectin interacted with PRMT5 and induced downregulation of E2F1 in cancer cells." (PMID 28335432, 2017). "In this study, we found that SHARPIN activates PRMT5 to specifically target histone H3R2 for monomethylation, which is responsible for the subsequent activation of cancer-related genes." (PMID 28903384, 2017). "Recently, it was also found that protein arginine methyltransferase 5 (PRMT5), an oncoprotein, expressing at high concentration in a number of human cancers, is negatively regulated by CHIP, which ubiquitinates and degrade PRMT5 via proteasomal degradation." (PMID 27757073, 2016). "Some preclinical evidence suggests legitimacy for combining therapy with PRMT5 and MAT2A inhibitors which may produce more robust responses in cancer patients." (PMID 41465382, 2025). "PRMT5 promotes various aspects of malignant cancer progression by dimethylating both histone and nonhistone substrates." (PMID 40756764, 2025). "This highlights a key regulatory role of PRMT5 in double-strand break repair via the Tip60-EP400 complex in MCC, supporting the concept of synergy between PRMT5 inhibitors and DNA-damaging agents in cancer cells." (PMID 40846633, 2025). "Selective inhibition of PRMT5 using small molecules such as EPZ015666 has demonstrated promising antitumor effects in preclinical models, including suppression of tumor growth and impaired cancer cell proliferation." (PMID 40791817, 2025). "Critically, whilst PRMT5 expression is generally elevated in cancer cells compared to non-transformed cells, its expression is further heightened within the BCSC population, suggesting that PRMT5 confers a survival advantage in this cell type." (PMID 39695328, 2025). "A unique mechanism, associated with the accumulation of MTA, which is not degraded by MTAP, sensitizes cancer cells to PRMT5 and MAT2A inhibitors." (PMID 41465382, 2025). "Similarly, selectivity for MTAP-deleted cancer cell lines was observed, with sensitivity to AMG193 correlated with a genetic dependency on PRMT5." (PMID 40157258, 2025). "Treatments for triple-negative breast cancer have recently used the EPZ015666 PRMT5 inhibitors, which impair cell proliferation in this type of cancer." (PMID 40869229, 2025).